CCL20 (C-C motif chemokine ligand 20)
Diseases named in the same sentence as CCL20 in open-access papers (continued):
Sharing a sentence is not in itself a finding about the gene and the disease.
colitis (continued). "Reflective of the increase in neutrophils, there was increased granulocyte colony-stimulating factor (G-CSF) and MIP-3α (CCL20) in both the BALF and plasma of mice with DSS colitis." (PMID 37063825, 2023). "Taraxacum officinale extract significantly reduced the expression of CCL20, CCR6, and CXCL1/5 in DSS-induced mice and alleviated colitis by modulating fatty acid metabolism and microorganisms." (PMID 36145301, 2022). "UC patients displayed excessive IL-21 in mucosal samples, leading the colonic epithelial cells to produce the macrophage inflammatory protein (MIP)-3a (also called CCL20), a chemokine upregulated in IBD patients or mice with chemically induced colitis." (PMID 33924897, 2021). "Thirdly, the ROC curve analysis showed that a combination of CCL20 and IL-17A was an effective panel for discriminating CRC cases from HD, and colitis from colorectal adenoma cases." (PMID 31387598, 2019). "RT‐PCR and IHC analysis validated that TOE up‐regulated the expression of Adh5, Aldh3a2 and Acox3, but down‐regulated the expression of CCL20, CXCL5, CCR6 and CXCL1 in DSS‐induced colitis." (PMID 31565850, 2019). "Hence, the substantially reduced Ccl20 expression in colons of Il6rαKO mice is a consequence of collapsed M2-type polarisation of IL-6Rα-deficient macrophages in CAC, thereby compromising CCR-6-expressing lymphocyte recruitment in colitis to promote tumourigenesis." (PMID 29695802, 2018). "In the colitis phase of CAC, IL-6-polarised M2-like macrophages express the chemokine CCL-20 that recruits CCR-6-expressing lymphocytes, further promoting CAC progression." (PMID 29695802, 2018). "The expression of the CCL20 protein in colonic mucosa was detected in UC patients and experimental dextran sulfate sodium- (DSS-) induced experimental colitis in mice in several studies." (PMID 25691899, 2015). "Our in vitro experiments suggest that intestinal M2 macrophages express CCL-20 in colitis via exposure to commensal antigens such as LPS and not as a consequence of direct IL-6-activated transcriptional traits." (PMID 29695802, 2018). "Indeed, along with the mucosal lesions, a moderate increment of mature CCL20 levels and the augmented transcription of INF-γ gene were revealed in the colonic tissue, confirming the typical features of T cell adoptive transfer colitis." (PMID 41011197, 2025). "IEC have been identified as the main producers of CCL20 in inflamed epithelium under different inflammatory conditions, and increased CCL20 expression is validated in colonic biopsies of UC and CD, but not in non-IBD colitis patients." (PMID 23977107, 2013).
ovarian carcinoma (25 papers, 2012 to 2026). A malignant neoplasm originating from the surface ovarian epithelium. "Elevated levels of circulating CXCL4 + CCL20 + CXCL1 in combination can discriminate among ovarian cancer patients those who are predisposed to shorter progression-free survival and overall survival." (PMID 40507922, 2025). "CCL20 gene encodes the chemokine C-C Motif Chemokine Ligand 20 and it was identified to play a role in metastasis and therapy resistance of ovarian cancer cells." (PMID 34439877, 2021). "Additionally, CCL20 has been associated with paclitaxel resistance in subgroups of ovarian cancer cell lines." (PMID 35565348, 2022). "Although there was no change in M1 marker expression in both THP1 and PBMCs, there was an increase in the production of CCL20 and IL1β that subsequently enhanced ovarian cancer cell migration." (PMID 39287565, 2024). "Cisplatin has also been shown to stimulate “classically-activated macrophages” (i.e., M1) to increase CCL20 cytokine production and enhance ovarian cancer cell migration via CCR6." (PMID 35565348, 2022). "Diagnostic performances and optimal cutoff values of serum CA125 and CCL20 levels for discriminating between benign disease and ovarian cancer." (PMID 36387204, 2022). "In ovarian cancer, cisplatin-stimulated macrophages increase the production of CCL20 and activate the expression of CCR6 on cancer cells, which promotes cell migration." (PMID 35841069, 2022). "Concordant with the serum protein level, the increased mRNA level of CCL20 was observed in ovarian cancers comparing with that in benign tissues." (PMID 36387204, 2022). "For example, a recent in vitro study found that cisplatin-induced release of CCL20 from classically activated macrophages promoted ovarian cancer cell and cell migration via the CCL20–CCR6 axis." (PMID 33924237, 2021). "Cisplatin-stimulated classically activated macrophages promote ovarian cancer cell migration by increasing CCL20 production, which activates its receptor CCR6 on ovarian cancer cells, triggering EMT." (PMID 32707869, 2020). "Ovarian cancer (OC) is one of prevalent tumors and this study aimed to explore CCL20’s effects on doxorubicin resistance of OC and related mechanisms." (PMID 30760665, 2019). "In conclusion, CXCR2-driven ovarian cancer progression in the peritoneal cavity involves NF-κB mediated CCL20 as a main chemokine network, which would lead to new approaches of ovarian cancer progression and treatment." (PMID 27723802, 2016). "Taken together, the progression of ovarian cancer in the peritoneal cavity involves NF-κB-mediated CCL20 as a main chemokine network, which is potentiated by CXCR2 expression." (PMID 27723802, 2016). "These facts support the observation that a high expression of CCL20 in SKCXCR2-derived tumor tissues can be involved in the progression of ovarian cancer." (PMID 27723802, 2016). "Unexpectedly, CXCR2 ligands such as CXCL1-3 and 8 were decreased in the progression of CXCR2-driven ovarian cancer compared to relatively constant CCL20 levels." (PMID 27723802, 2016). "One of the primary findings in this study is that in these four ovarian cancer cell lines, CCL20, CXCL1-3 and CXCL8 were the major chemokines that responded to EGF or TNF by involving NF-κB, Akt and Erk signaling pathways." (PMID 23800251, 2013). "The chemokine network revealed that ovarian cancer cells commonly expressed high levels of proinflammatory chemokines such as CCL20, CXCL1-3 and CXCL8 in response to EGF or TNF." (PMID 23800251, 2013). "Our results indicate that ovarian cancer cells induce CCL20, CXCL1-3 and CXCL8 as the primary chemokines in response to EGF or TNF." (PMID 23800251, 2013).
ovarian carcinoma (continued). "The results revealed high expression of chemokines in the following ovarian cancer cell lines: CCL20 and 28, CXCL1, 2, 3 and 8 in OVCAR-3 cells; CCL28 and CXCL1 in SKOV-3 cells; CXCL1, 2 and 8 in CaOV-3 cells; and CXCL2 in TOV-21G cells." (PMID 23300534, 2012). "Additionally, CCL20 promotes ovarian cancer resistance by modulating ABCB1 expression and Notch1 signaling pathway." (PMID 40968783, 2026). "Other chemokines potentially involved in cancer progression include CCL18, which promoted ovarian cancer migration, CCL20, which promoted both metastasis and chemotherapy resistance, and CXCL8 (IL-8), which may contribute to peritoneal metastasis." (PMID 40689422, 2025). "As reported, CCL20 induces EMT in ovarian cancer cells and contributes to tumor progression." (PMID 36045408, 2022). "Additionally, in ovarian cancer (OC) patients, circulating CXCL1, CCL4, and CCL20 are elevated in serum specimens, which are associated with shorter recurrence-free survival (RFS) and OS." (PMID 36612163, 2022). "Concurrently, the analyzed results showed that there is shift of dominant chemokines from CXCL1-3 and 8 (CXCR2 ligands) to CCL20 between pre-spreading (in vitro) and post-spreading (in vivo) in ovarian cancer, as demonstrated in our mouse peritoneal spreading model." (PMID 27723802, 2016). "Probably, CXCR2 positive ovarian cancer cells could potentiate the NF-κB mediated CCL20 in proinflammatory tumor microenvironment via interaction between ovarian cancer and cancer-associated stromal cells compared to CXCR2 negative cells." (PMID 27723802, 2016). "In ovarian cancer, CCL20 is one of the primary chemokine induced via NF-kB pathway." (PMID 27259239, 2016). "In ovarian cancer, CCL20 could promote tumor progression in the peritoneal cavity." (PMID 33123272, 2020). "Therefore, high levels of TNF and frequent overexpression of EGFR observed in ovarian cancer could provide the fundamental basis for the higher expression of CCL20 in SKCXCR2-derived tumor tissues." (PMID 27723802, 2016). "Therefore, we first asked whether NF-κB plays critical role in CXCR2-mediated CCL20 regulation to elucidate the signaling pathway involved in the induction of CCL20 during ovarian cancer progression." (PMID 27723802, 2016). "This is associated with an increase in CCL20/LARC expression by CXCL1, indicating some change in the expression of secretory factors during ovarian cancer development, in which CXCL1 is crucial at its beginning and CCL20/LARC at later stages." (PMID 37108425, 2023). "The study aimed to investigate the potentiality of chemokines, including MCP-1, CCL15, CCL20, and CXCL14, as biomarkers for differential diagnosis between benign tumors and ovarian cancer (OC)." (PMID 36387204, 2022). "In vitro, cisplatin stimulated human macrophage-like THP-1 to become classically activated (CAMs) and to produce CCL20, chemokine ligand 20 (macrophage inflammatory protein-3 (MIP3A), that activates CCR6 on ovarian cancer cells, promoting EMT and migration." (PMID 33194645, 2020). "Pharmacological blockage of CCL20 on cisplatin-stimulated activated macrophages and siRNA-mediated inactivation of CCR6 on cancer cells effectively abrogate ovarian cancer cell migration induced by cisplatin-stimulated activated macrophages." (PMID 32707869, 2020). "Our previous study demonstrated that proinflammatory chemokines such as CCL20, CXCL1-3 and CXCL8 are elicited in ovarian cancer cells via NF-κB- and EGFR-activated signaling pathways." (PMID 27723802, 2016). "Our previous studies demonstrated that TNF activated the nuclear factor-κB (NF-κB) signaling to induce proinflammatory chemokines such as CCL20, CXCL1-3 and CXCL8 in ovarian cancer cells." (PMID 27723802, 2016). "Our results indicate that CCL20, CXCL1-3 and CXCL8 are the primary chemokines induced by EGF or TNF and are elicited in these ovarian cancer cells via NF-κB, Akt and Erk signaling pathways." (PMID 23800251, 2013).
ovarian carcinoma (continued). "Despite either no or little activation of NF-κB, EGF is likely to broadly induce CCL20, CXCL1-3 and CXCL8 through Akt/Erk activation in ovarian cancer cells." (PMID 23800251, 2013). "In this study, we showed that EVs from ovarian cancer cells upregulated genes related to the inflammatory response, including immune cell–attracting cytokines (CCL2, CCL3/L1, CCL15, CCL18, and CCL20), interleukins (IL1B and IL32), and cell–cell adhesion transcripts (VCAM1 and ICAM1)." (PMID 40689422, 2025). "The human ovarian cancer cell lines (pre-spreading in vitro) showed dominant expression levels of CXCL1-3, 8 and CXCR4, while EOC (post-spreading in vivo) had higher levels of CCL20, CXCL17 and CXCR4." (PMID 27723802, 2016). "Based on the synergistic increase of CCL20 and CXCL8 in response to EGF and TNF, CCL20 and CXCL8 may be the dominant chemokines found in ovarian cancer cells with abundant TNF, and/or activation of the EGFR." (PMID 23800251, 2013).
Obesity (24 papers, 2013 to 2025). Accumulation of substantial excess body fat. "CCL17 gene variant rs223828 T and CCL20 gene variant rs6749704 T have been implicated in obesity in Tatars." (PMID 34834553, 2021). "CCL20 is assumed to contribute to the development and progression of obesity-associated insulin resistance, during which its levels were found to be raised in adipose tissue, plasma as well as in pancreatic β-cells." (PMID 31022842, 2019). "CCL20 is an adipochemokine whose expression is modulated by an anatomic arrangement of adipose tissue and by obesity severity." (PMID 34834553, 2021). "For instance, the expression of CCL5 and CCL20 has been associated with fatty liver disease, while CXCL5 is an adipose tissue derived factor associated with obesity." (PMID 32764789, 2020). "Obesity-induced interleukin-6 (IL-6) shifts macrophage polarisation towards tumour-promoting macrophages that produce the chemokine CC-chemokine-ligand-20 (CCL-20) in the CAC microenvironment." (PMID 29695802, 2018). "Here the authors show in mouse models that obesity-induced interleukin-6 alters macrophage function to enhance CCL-20/CCR-6-mediated recruitment of B cells and γδ T cells, thereby promoting gut inflammation and CAC progression." (PMID 29695802, 2018). "Our results extend initial observations of an approximate tenfold increase in expression of hepatic CCL20 transcript levels in eight samples from patients with NASH to a large cohort of patients with extreme obesity." (PMID 29690903, 2018). "CCL20 is elevated in the skin during obesity and type 2 diabetes." (PMID 40073267, 2025). "Cluster C6 expressed CCL20, chemokine elevated during obesity." (PMID 37063898, 2023). "Patient’s visceral fat area correlated with secreted factors including CCL20, suggesting that obesity status may alter the tumour microenvironment (TME)." (PMID 33540635, 2021). "CCL20 represents a new candidate molecule that may be involved in the pathogenesis of NAFLD fibrosis in the population with obesity that was investigated." (PMID 29690903, 2018). "We extended this exploration to pre-adipocytes, CD31+ endothelial cells and mature adipocytes, focusing on a set of inflammation-related genes (CCL2, CCL20, IL-8, IL-6 and pro-IL-1β) selected among genes known to be up-regulated in adipose tissue with human obesity." (PMID 28592801, 2017). "CCL20 produced by stellate cells in response to lipid loading may therefore be a key mechanism in the fibrotic progression of NAFLD in response to the increased caloric intake in extreme obesity." (PMID 29690903, 2018). "One of the genes modulated in epidermal γδ T cells during obesity and type 2 diabetes is CCR6, which is the receptor for CCL20." (PMID 40073267, 2025). "Collectively, our study assigns obesity-induced IL-6 as a modulator of the TME in CAC via macrophage polarisation and successive lymphocyte recruitment via the CCL-20/CCR-6 axis." (PMID 29695802, 2018). "During the progression of MASLD, mature adipocytes release chemokines, such as CCL20, and other soluble mediators, stimulating lymphocyte migration in adipose tissue through CCR6, resulting in obesity-related inflammation, such as insulin resistance, and the occurrence of MASLD." (PMID 38550602, 2024). "It is noteworthy that both CCL20 and PAI-1 were also found to be elevated in pHNECs obtained from obese individuals, implicating an important role for these mediators in influenza infection in obesity." (PMID 37680710, 2023). "Indeed, suppression of the TM4SF5 downstream effector CCL20 leads to the blockade of HFD-mediated NASH phenotypes, and Tm4sf5−/− KO mice show protection from diet-induced obesity." (PMID 37670786, 2023). "High levels of insulin-like growth factor 1 (IGF1) and insulin in obesity downregulate Glycogen synthase kinase 3 beta (GSK3B) activity by phosphorylating its serine residue, thereby altering the IL-17 signaling pathway, including upregulation of CXCL1, CCL20, and IL-6 expression." (PMID 37680632, 2023).
Obesity (continued). "Obesity-induced IL-6 expression promotes the polarization of M2 macrophages and induces secretion of the chemokine CC-chemokine ligand 20 (CCL20) in the CAC microenvironment; CCL20 recruits CC-chemokine receptor 6 (CCR6)-expressing B cells and γδ T cells via chemotaxis, leading to CAC progression." (PMID 34445193, 2021). "Interestingly, all tissues of T2D patients showed altered expression of genes involved in the inflammation response—such as SOCS1 in WB; CCL20 and SLAMF1 in SAT; ACP5, FOS, and JUN in VAT; and PLA2G2A in LT, showing the relevance of the systemic chronic inflammation in obesity and T2D." (PMID 29466957, 2018).